NLRP3 (NLR family pyrin domain containing 3)
Diseases named in the same sentence as NLRP3 in open-access papers (continued):
Sharing a sentence is not in itself a finding about the gene and the disease.
liver fibrosis (continued). "We characterized a functional link of age‐mediated defects in SIRT1 to the NLRP3 inflammasome during age‐related liver fibrosis." (PMID 36999514, 2023). "Nlrp3 deletion in myeloid-derived cells led to reduced liver fibrosis and reduced markers for HSC activation (Col1a, Col3a)." (PMID 37664463, 2023). "All the genes were downregulated when NLRP3 was silenced, implying that NLRP3 had an important impact on liver fibrosis." (PMID 36983568, 2023). "Aldosterone can induce HSC activation and liver fibrosis in mice by promoting NLRP3 assembly and expression." (PMID 37081882, 2023). "The activation of the NLRP3 inflammasome plays an important role in various liver diseases, including nonalcoholic fatty liver and liver fibrosis." (PMID 36834849, 2023). "The absence and inhibition of NLRP3 attenuate hepatic fibrosis in murine models of aging and Schistosoma japonicum infection, respectively." (PMID 37492223, 2023). "In studies in aging mice, ginsenoside Rg1 reduced NOX4, NF-κB, NLRP3 inflammatory expression levels, thereby improving aging-induced liver fibrosis." (PMID 38054830, 2023). "Our previous studies found that tenofovir alafenamide fumarate (TAF) and tenofovir disoproxil fumarate (TDF) protected liver injury by decreasing NF-κB/NLRP3 inflammasome signaling pathways, thereby attenuating liver fibrosis." (PMID 36983568, 2023). "This study aimed to investigate the effects of Asp on CCl4-induced liver fibrosis in mice and HSCs via the NF-κB/NLRP3 signaling pathway." (PMID 36983568, 2023). "Accumulating evidence indicates that the activation of NLRP3 inflammasome in macrophages plays a vital role in driving chronic liver inflammation and the subsequent liver fibrosis." (PMID 37122751, 2023). "The direct role of NLRP3 inflammasome in liver fibrosis has also been demonstrated in other experimental models of liver fibrosis." (PMID 37492223, 2023). "Mechanistically, deletion of SIRT1 in hepatocytes resulted in NLRP3 and IL‐1β induction, pro‐inflammatory response, and severe liver fibrosis in young mice, mimicking the ability of aging to impair the resolution of established fibrosis." (PMID 36999514, 2023). "Not only NLRP3 inflammasome but also other inflammasome complexes are involved in liver injury and liver fibrosis." (PMID 35707547, 2022). "The upregulation of this IRE1-mediated NF-κB has also been shown to enhance NLRP3 expression in a liver fibrosis model." (PMID 36421428, 2022). "Although NLRP3 has been proven to be involved in the process of liver fibrosis, its role and mechanism in neurogenic bladder fibrosis are unclear." (PMID 36497096, 2022). "More importantly, growing evidence suggests a close correlation between NLRP3 inflammasome activation as well as its downstream effectors and liver fibrosis progression." (PMID 36429008, 2022). "Staining signals of the pyroptosis mediator NLRP3 alone with S100A8 were gradually increased with the aggravation of liver fibrosis in mouse models from 4 to 8 weeks." (PMID 36429008, 2022). "By phosphorylating Smad2/3, the NLRP3 inflammasome causes the expression of α-SMA in HSCs and the conversion of hepatocytes to EMT, which produces collagen type 1 and results in liver fibrosis." (PMID 36110858, 2022). "As expected, injection of MCC950 significantly attenuated liver injury, especially liver fibrosis and improved liver function, indicating that NLRP3, as the executor of pyroptosis, is an advancing prevention target for liver fibrosis." (PMID 36429008, 2022). "Melatonin is able to alleviate liver fibrosis caused by Txnrd3 knockdown and nickel exposure through the activation of the IRE1/NF-κB/NLRP3 and PERK/TGF-1 axis." (PMID 36290765, 2022). "Oxidative stress injury of Mitochondria and activation of NLRP3 inflammatory body play an important role in the development of liver fibrosis." (PMID 35694250, 2022). "The compounds from Fructus Aurantii significantly inhibited liver inflammation in liver fibrosis mice by reducing NLRP3 expression." (PMID 36106027, 2022).
liver fibrosis (continued). "Altogether, these data suggested that the effect of SSd on NLRP3 inflammasome activation in liver fibrosis was likely mediated through the regulation of mitochondrial ROS level." (PMID 35694250, 2022). "The HFSCD+CCl4-treated rats showed fat accumulation in the liver, elevated levels of inflammatory mediators, NLRP3 inflammasome activation, antioxidant dysregulation, and liver fibrosis." (PMID 36077357, 2022). "Increased TNF and IL-17 expression, which is mediated by the NLRP3 inflammasome, is a major contributor to liver fibrosis and inflammation." (PMID 36110858, 2022). "In vivo, NLRP3-/- mice had reduced chemically-induced liver fibrosis while conditional NLRP3 knock-in mice expressing an hyperactive NLRP3 present HSC activation with increased collagen deposition in the liver." (PMID 36313762, 2022). "Based on the previously reported regulatory role of DNTs in an inflammatory response, this study aimed to reveal the mechanism of action of NLRP3 in liver fibrosis." (PMID 35371052, 2022). "In contrast, natural killer T (NKT) cells had dual roles in regulating liver fibrosis via activating the NLRP3 inflammasome." (PMID 35707547, 2022). "The NLRP3 inflammasome is closely related to HSCs activation and is a key mechanism in the regulation of hepatic fibrosis progression." (PMID 35138513, 2022). "Evidence supports that NLRP3 inflammasome-dependent pyroptosis is involved in the development of liver fibrosis." (PMID 36429008, 2022). "In carbon tetrachloride-induced liver fibrosis, alpinitin activates the Nrf2 pathway while suppressing the NLRP3 pathway, which results in alpinitin’s ability to exhibit anti-inflammatory, anti-oxidative, and anti-angiogenic actions." (PMID 36290765, 2022). "S100A9, released from necroptosis in the liver, binds to NLRP3 on HSCs and myofibroblasts, triggering an inflammatory response and generating extracellular collagen synthesis, resulting in liver fibrosis." (PMID 36110858, 2022). "Studies have shown that ursolic acid (UA) can regulate EMT or MFB via Rho, improve the integrity of the intestinal barrier, reduce intestinal flora disorders, and modulate the NOX4/NLRP3 inflammatory vesicle signaling pathway to attenuate liver fibrosis." (PMID 35529927, 2022). "The activation of NLRP3 inflammasome and pyroptosis has been involved in the progression of liver fibrosis and its end-stage cirrhosis, which is among the main etiologies for liver transplantation (LT)." (PMID 36430874, 2022). "It has been confirmed that Rg1 ameliorated aging-induced liver fibrosis by inhibiting the NLRP3 inflammasome in mice." (PMID 35736894, 2022). "PA can moderate PBC-induced liver fibrosis in mice and probably work by muffling the formation of NLRP3." (PMID 35195182, 2022). "We observed the enhanced expression of NLRP3 in patients with liver fibrosis compared to HCs and NLRP3 was mainly localized to hepatocytes and KCs but not HSCs, especially KCs, indicating that KCs are major cell types that undergo pyroptosis." (PMID 36429008, 2022). "Recent literature found that NLRP3 inflammasome activation induced by mitochondrial oxidative stress plays an important role in the development of liver fibrosis." (PMID 35694250, 2022). "Numerous studies have indicated that the activation of the NLRP3 inflammasome is a critical contributor to the development of liver fibrosis." (PMID 36160411, 2022). "Activation of NLRP3 in HSCs caused by schistosome infections depends on the Dectin-1/Syk signaling pathway, while inhibition of NLRP3 inflammasome activation significantly reduces egg granulomas and liver fibrosis." (PMID 36389166, 2022). "Collectively, these data suggest that MALAT1 is essential for activating M1 macrophages and NLRP3 inflammasome-mediated pyroptosis in CCl4-induced liver fibrosis." (PMID 34839365, 2021).
liver fibrosis (continued). "Taken together, these data suggested Sch B can reduce S. mansoni-induced inflammation by inhibiting activation of NLRP3 inflammasome and pyroptosis, thereby displaying a potential role to inhibit S. mansoni-induced liver fibrosis." (PMID 34161342, 2021). "In conclusion, our study demonstrated that MyD88 in macrophages promoted the development of liver fibrosis via activating NLRP3 inflammasome in HSCs." (PMID 34830293, 2021). "A small molecule inhibitor of the NLRP3 inflammasome (MCC950) shows potential as a drug for liver fibrosis." (PMID 34193972, 2021). "Our results indicated that the NLRP3 inflammasome in HSCs can directly regulate their activation and contribute to liver fibrosis." (PMID 34830293, 2021). "Strikingly, accumulating evidence has shown that NLRP3 inflammasome levels are increased during experimental liver fibrosis, where they are prominently expressed in Kupffer cells and HSCs." (PMID 33499218, 2021). "Since Sch B has been shown to ameliorates inflammasome activation in various inflammatory models, to also verify the protective effects of Sch B against S. mansoni-induced liver fibrosis, we examined the effects of Sch B on the NLRP3 inflammasome pathway." (PMID 34161342, 2021). "Now, for the first time, our data reveal that chronic administration of aspartame to mice induces NLRP3 inflammasome activation and liver fibrosis in a mechanism mediated by oxidative stress." (PMID 33499218, 2021). "System Xc inhibitors, including sulfasalazine and erastin, blocked activation of the NLRP3 inflammasome, suggesting that these inhibitors have the potential to cure liver fibrosis." (PMID 34193972, 2021). "In our study, CCI4 was injected into WT mice and NLRP3−/- mice to establish liver fibrosis models, and the results showed that the expression of the NLRP3 inflammasome increased in mice with liver fibrosis." (PMID 34530693, 2021). "Ang II stimulates NADPH oxidase 4 (NOX4)-derived ROS and mitochondria-dependent ROS accumulation to aggravate hepatic fibrosis by activating HSCs through the IL-1β/NLRP3/Smad pathway and the TLR4/MyD88/NF-κB pathway." (PMID 34944017, 2021). "Our study showed that UA improved the intestinal bacteria by inhibiting the NOX4/NLRP3 inflammasome signaling pathway, thereby restoring liver function and slowing the occurrence and development of liver fibrosis." (PMID 34530693, 2021). "Our study showed that the intestinal bacteria changed during liver fibrosis, and this change was closely associated with UA-mediated inhibition of the NOX4/NLRP3 inflammasome signaling pathway." (PMID 34530693, 2021). "NLRP3 inflammasome activation by ER stress contributed to hepatocyte death, inflammation, and ultimately liver fibrosis." (PMID 33567666, 2021). "The NLRP3 inflammasome has been identified as an essential trigger for liver inflammation in patients with non-alcoholic fatty liver disease and liver fibrosis." (PMID 34193972, 2021). "The NLRP3 inflammasome has been identified as a trigger for liver fibrosis in patients with non-alcoholic fatty liver disease." (PMID 34193972, 2021). "The essential findings of the present study are that an anti-NLRP3 approach in NASH can arrest established liver fibrosis and chronic inflammation in ApoE-/- mice." (PMID 34513923, 2021). "The changes in the expression of liver fibrosis-related indicators were similar, suggesting that NLRP3 is an important profibrotic factor in the process of liver fibrosis." (PMID 34530693, 2021). "Growing evidence supports a central role of NLRP3 activation and downstream effectors in the development of liver fibrosis." (PMID 34830293, 2021). "It has been shown that the level of NLRP3 expression, among other inflammasomes, is augmented during experimental liver fibrosis." (PMID 34830293, 2021). "In summary, this study showed that the NOX4/NLRP3 inflammasome signaling pathway is essential in the development of liver fibrosis and an important target for the regulation of intestinal bacteria." (PMID 34530693, 2021).
liver fibrosis (continued). "To explore the role of the NOX4/NLRP3 inflammasome pathway in liver fibrosis, we measured the expression of NOX4/NLRP3 in the three groups of mice." (PMID 34530693, 2021). "The NOD-like receptor protein 3 (NLRP3) inflammasome is emerging as a therapeutic target in liver fibrosis." (PMID 34193972, 2021). "Glycyrrhizin and its metabolites glycyrrhetinic acid can attenuate non-alcoholic steatohepatitis-induced liver fibrosis, which is mediated by suppression of NLR family pyrin domain-containing 3 (NLRP3) inflammasome and restoration of bile acid homeostasis." (PMID 34868982, 2021). "The activation of NOD-like receptor family pyrin domain-containing three (NLRP3) inflammasomes has been shown during Schistosoma-infected liver fibrosis." (PMID 34161342, 2021). "Recently, numerous studies have shown that NLRP3 inflammasome plays an important role in the pathogenesis of liver diseases, including non-alcoholic fatty liver disease, liver fibrosis, cirrhosis, and hepatocellular carcinoma." (PMID 32211410, 2020). "We previously proved that MCC950, a selective NLRP3 inhibitor, alleviates liver fibrosis and injury in experimental liver cholestasis induced by bile-duct ligation (BDL) in mice." (PMID 32296329, 2020). "In mice with MCD diet-induced NASH, glycyrrhizin and its metabolite glycyrrhetinic acid can significantly decrease bile acids accumulation, thus inhibiting the activation of NLRP3 inflammasome to attenuate liver fibrosis." (PMID 33390969, 2020). "Accumulated evidences indicate that NLRP3 inflammasome plays an important role in the pathogenesis of liver fibrosis/cirrhosis." (PMID 32211410, 2020). "MCC950, an agent that can block NLRP3 inflammasome, decreases the expression of liver caspase-1 and the numbers of macrophages and neutrophils, ultimately alleviating liver fibrosis." (PMID 32211410, 2020). "These factors are intimately related to the activation of NLRP3 inflammasome, prospectively, it will be a splendiferous choice to prevent and treat liver fibrosis by probing the inhibition of NLRP3 inflammasome activity." (PMID 32211410, 2020). "NLR family pyrin domain containing 3 (NLRP3) inflammasome accompanies chronic liver injury and is a critical mediator of inflammation-driven liver fibrosis." (PMID 32695095, 2020). "Angiotensin II (Ang II), a key player in RAS, induces the generation of NADPH oxidase 4 (NOX4)/mitochondria-derived ROS and aggravates liver fibrosis, while NLRP3 inflammasome activation is tightly connect with NOX4/mitochondria-derived ROS." (PMID 32211410, 2020). "During the pathogenesis of NAFLD, liver fibrosis, and cirrhosis, the activation of NLRP3 inflammasome accelerates the pathological progression aggravating the symptoms of liver diseases on human body." (PMID 32211410, 2020). "As one of many important NLRP3 inflammasome activators, ROS have been reported to promoting the chronic liver disease, including hepatic fibrosis." (PMID 32963808, 2020). "Put together, these data suggest that VDR activation by calcipotriol alleviates liver fibrosis and injury in cholestasis through inhibition of NLRP3 signal, and calcipotriol inhibits HSC activation by inhibiting NLRP3 pathway both directly and indirectly." (PMID 32296329, 2020). "NLRP3 inhibition delayed hepatic fibrosis with lowered fibrotic markers and macrophage and neutrophil infiltration in both NASH murine models." (PMID 33353156, 2020). "Activated caspase-1, IL-18, and IL-1β signaling are also pivotal to the development of liver fibrosis resulting from the activation of NLRP3 inflammasome." (PMID 32211410, 2020). "Both quercetin and pelargonidin contribute to alleviating hepatic fibrosis by upregulating Nrf2 to inhibit NLRP3 inflammasome activation." (PMID 33390969, 2020). "NF-κB signaling is also important for the pathological process of liver fibrosis, while NLRP3 inflammasome activation is accompanied by the upregulation of NF-κB signaling." (PMID 32211410, 2020).
liver fibrosis (continued). "Recent results have shown that the expression of hepatic NLRP3 inflammasome components increases during liver fibrogenesis, and NLRP3 expression level is closely correlated with the severity of liver fibrosis." (PMID 32695095, 2020). "The inhibition of Ang II alleviates liver fibrosis by reducing the generation of Ang II-induced ROS and influencing NLRP3 inflammasome activation." (PMID 32211410, 2020). "Recent studies have shown that the inflammasome complex NLRP3 in liver stellate cells can directly regulate its activation and contribute to liver fibrosis." (PMID 32977490, 2020). "Nuclear factor-κB (NF-κB), a transcription factor, regulates the formation of NLRP3 inflammasome and takes part in the progression of liver fibrosis." (PMID 30635040, 2019). "Recently, studies have shown that a western diet can evoke NLRP3 inflammasome activation in liver fibrosis." (PMID 30635040, 2019). "Using MCC950 and NLRP3 siRNA, NLRP3 inflammasome and liver fibrosis can be reduced in nonalcoholic steatohepatitis (NASH) and S. japonicum mice, respectively." (PMID 30635040, 2019). "NOD-like receptor protein 3 (NLRP3) inflammasome was reported as expressed in schistosomiasis-induced liver fibrosis (SSLF)." (PMID 30635040, 2019). "To further elucidate the mechanism by which infection with S. japonicum induces NLRP3-dependent liver fibrosis, we examined the role of NF-κB in this process." (PMID 30635040, 2019). "The second problem relates to how MCC950 can alter NLRP3 inflammasome and liver fibrosis of S. japonicum differently depending on the time of MCC950 administration." (PMID 30635040, 2019). "In our study, the BDL operation significantly increased NLRP3 inflammasome signal pathway expression, resulting in liver fibrosis." (PMID 31827690, 2019). "We confirm that NLRP3 inflammasome was expressed in liver fibrosis of mice infected with S. japonicum." (PMID 30635040, 2019). "Currently, a large number of studies focus on NLRP3 inflammasome expression and its activation mechanisms but few have examined how NLRP3 inflammasome regulates liver fibrosis." (PMID 30635040, 2019). "Collectively, these results suggest that NLRP3 inflammasome formation in the liver and liver fibrosis were the result of egg deposition and that the inflammasome contributed to the pathogenesis of schistosomiasis." (PMID 30635040, 2019). "In fact, recent studies have found that NLRP3 inflammasome is present in liver fibrosis induced by S. japonicum infection." (PMID 30635040, 2019). "In summary, we have demonstrated that the NLRP3 inflammasome takes part in the process of S. japonicum induced liver fibrosis via NF-κB signaling." (PMID 30635040, 2019). "Here, we aim to provide more data to deeply understand the effects of NLRP3 on the process of liver fibrosis in schistosomiasis." (PMID 30635040, 2019). "We have demonstrated that NF-κB is involved in NLRP3 inflammasome induced liver fibrosis of S. japonicum-infected mice." (PMID 30635040, 2019). "As NLRP3 inflammasome participation in liver fibrosis triggered by S. japonicum is principally derived from KCs, we analyzed the co-localization of NF-κB and the KCs marker F4/80 in liver tissues." (PMID 30635040, 2019). "The third issue deals with how the NLRP3 inflammasome is principally involved in liver fibrosis of S. japonicum derived from KCs." (PMID 30635040, 2019). "Our animal studies found that NLRP3 inflammasome activation not only participated in HFD-induced hepatitis and liver fibrosis but also caused steatosis in the liver." (PMID 30140364, 2018). "In particular, IL-1β promotes the differentiation of Th17 cells to secret interleukin-17 (IL-17), which is a critical proinflammatory cytokine in amplifying inflammation responses and perpetuating liver fibrosis driven by NLRP3 inflammasome activation." (PMID 30319645, 2018).